APC (APC regulator of Wnt signaling pathway)
Diseases named in the same sentence as APC in open-access papers (continued):
Sharing a sentence is not in itself a finding about the gene and the disease.
glioma (continued). "In this study, we found that upregulation of miR-4476 in human gliomas is correlated with tumor progression, and overexpression of miR-4476 promotes the proliferation, migration, and invasion of glioma cells through a miR-4476/APC/β-catenin/c-Jun positive feedback loop." (PMID 32327666, 2020). "Furthermore, western blot showed miR-4476 inhibitor suppressed both EMT and Wnt/β-catenin/cell-cycle pathway activity in glioma cells, while co-transfection with APC siRNA reversed these effects." (PMID 32327666, 2020). "Furthermore, miR-4476 expression was positively correlated with c-Jun expression, but negatively correlated with that of APC, which further supports the existence of a miR-4476/APC/β-catenin/c-Jun positive feedback loop in gliomas." (PMID 32327666, 2020). "In our clinical tissue samples, patients with high APC expression tended to have longer survival times than those with low APC expression, while high c-Jun expression appeared to be an unfavorable prognosis factor in glioma patients." (PMID 32327666, 2020). "Whether over-expressed YAP competes with β-catenin for binding AXIN/APC/GSK3β complex and then releases β-catenin from the complex in glioma context?" (PMID 28962630, 2017). "Taken together, our findings suggest that mir-218-2 promotes glioma progression through the CDC27/APC ubiquitin–proteasome pathway, and promotes the invasion, migration, and actin organization through the modulation of cell junction and focal adhesion proteins." (PMID 27974673, 2017). "The upregulated YTHDF2 binds to the mRNA of the negative regulatory factors APC and GSK3β in the Wnt-β-Catenin pathway that are modified by m6A, promoting their degradation and thereby activating the Wnt-β-Catenin pathway, ultimately promoting glioma migration, invasion, and EMT." (PMID 38637831, 2024). "Furthermore, silencing APC reversed the suppressive effects of miR-4476 inhibitors in glioma." (PMID 32327666, 2020). "No APC mutations were found in any of the 13 glioma cultures that could have contributed to the accumulation of cytoplasmic β-catenin." (PMID 22919349, 2012). "While our study did not explore the overall impact of PRMT6 on m6A modifications in glioma cells, we found that PRMT6 affects the m6A modification of APC and GSK3β mRNA, as overexpression of PRMT6 reduces the m6A levels on these mRNAs." (PMID 38637831, 2024). "Modulation of these miRs that target Wnt inhibitors FZD6 and APC affects nuclear localization of β-catenin in both PN and MES glioma spheres." (PMID 27698350, 2016). "Finally, we examined whether APC also plays a role in the growth and signalling of glioma spheres." (PMID 27698350, 2016). "Of 28 genes identified as hallmark EGFR signaling cascade genes, 21 demonstrated significant 3′ UTR lengthening, 7 displayed no change and 1 displayed significant shortening in APC low expression low-grade glioma samples." (PMID 39375704, 2024). "Nevertheless, whether dysregulated miRNA-4476 expression has a role in gliomagenesis or glioma progression, and whether this role is mediated by APC interaction in glioma, have not been reported." (PMID 32327666, 2020). "The APC/CCdc20 regulates the UPS-dependent degradation of several proteins that drive the cell cycle, including cyclins A and B, while other APC/CCdc20 substrates (geminin, survivin, polo and aurora kinases) or regulators (Emi1, RASSF1A) are overexpressed in high grade gliomas." (PMID 22817864, 2012).
thyroid cancer (29 papers, 1994 to 2026). "The APC gene mutation responsible for FAP also contributes to the development of thyroid cancer by affecting cell growth regulation, leading to the formation of polyps in the colon and malignancies in other tissues, including the thyroid." (PMID 39156381, 2024). "The pathogenesis of cribriform morular thyroid cancer involves the Wnt/β-catenin pathway, often associated with potential germline or sporadic APC mutations, and/or with functionally equivalent genes such as CTNNB1 and AXIN1." (PMID 38835742, 2024). "Most FAP patients with thyroid cancers have germline mutations of the APC gene in exon 15 before codon 1220." (PMID 36864485, 2023). "(c) In FAP-associated patients, the germline mutation sites of the APC gene are consistent with the region associated with thyroid cancer." (PMID 36864485, 2023). "It is considered that the loss of function of the APC gene is associated with gain of function of RET/PTC in FAP-associated thyroid cancer." (PMID 36864485, 2023). "We report a de novo FAP case with thyroid cancer presenting atypically aggressive features harboring a novel APC mutation and review APC germline mutations in patients with FAP-associated thyroid cancer." (PMID 36864485, 2023). "Miyaki and coworkers noted that each carcinoma had a different somatic mutation of the APC gene, suggesting independent development of multicentric thyroid carcinomas in FAP patients." (PMID 36864485, 2023). "Here we report a sporadic case of cribriform morular thyroid carcinoma with a poorly developed morular pattern and two novel oncogenic somatic variants of the APC gene." (PMID 36689061, 2023). "Another study showed that the risk of developing thyroid cancer is higher in individuals with APC mutations at the 5’ end, near codon 528, and that this risk further increases in subjects harboring a mutation at codon 1061." (PMID 35626065, 2022). "Most APC germline mutations associated with thyroid cancer occur in the 5′-portion of exon 15, in the same genomic area associated with CHRPE (codons 463–1387), and codon 1061 is also a hot spot for both C-MV of TC and hepatoblastoma." (PMID 33495912, 2021). "In more than 80% of patients with FAP and thyroid cancer, APC germline gene mutations occur between codons 140 and 1513 (largely outside the MCR)." (PMID 33495912, 2021). "This is, however, the first analysis that attempts to define the actual risk of thyroid cancer associated with specific APC mutations in FAP patients whilst adjusting for the frequency distribution of APC mutations in FAP patients." (PMID 24093640, 2013). "There is increased risk for thyroid cancer in individuals with APC mutations at the 5' end (proximal to codon 528) along with the established high risk group harboring mutation at codon 1061." (PMID 24093640, 2013). "We compared the prevalence of APC mutations in the published patients with thyroid cancer to the prevalence of the same mutation in the reference population." (PMID 24093640, 2013). "The aims are to better understand gene mutations associated with thyroid cancer and to better use specific APC gene mutations to refine surveillance recommendations." (PMID 24093640, 2013). "It is noteworthy that our search revealed only 48 published patients with FAP, a specified APC gene mutation and thyroid cancer." (PMID 24093640, 2013). "Components of the Wnt signalling pathway such as β-catenin and APC have been found to be mutated in many cancers including thyroid cancer." (PMID 19055826, 2008). "In thyroid cells, aberrant Wnt signaling due to APC mutations may contribute to uncontrolled cellular growth, driving the development of thyroid carcinomas, including papillary thyroid carcinoma." (PMID 39860595, 2025). "Additionally, more than 30% of cribriform morular thyroid carcinoma tumors harbor somatic APC mutations, whereas up to 50% of cancer cells harboring somatic APC mutations can be found in patients with germline APC aberrations." (PMID 38835742, 2024).
thyroid cancer (continued). "The clinical features of cribriform morular thyroid carcinoma may be associated with FAP due to APC mutations." (PMID 38835742, 2024). "Although progresses have been made in identifying the relationship between the development of thyroid cancer and specific mutant regions, TC may occur in patients with germline mutations throughout the APC gene." (PMID 36864485, 2023). "Previous studies have shown thyroid cancer incidence to be increased in patients with APC variants." (PMID 37277882, 2023). "APC mutations are rarely detected in sporadic thyroid cancers and may play a role in thyroid cancer development." (PMID 35626065, 2022). "In addition, we found mutations associated with increased risk of thyroid cancer: three cases harbored alterations of APC (three cmvPTC) and two cases harbored biallelic mutations of DICER1 (one fvPTC and one FTC)." (PMID 35015563, 2022). "On comparing the prevalence of APC mutation in the population of FAP patients with thyroid cancer and the prevalence of the same mutation in the reference population an increased odds ratio was evident in individuals harboring an APC mutation at codon 1061 (OR: CI 4.1: 1.7-8.9)." (PMID 24093640, 2013). "This study shows that there is an increased risk of thyroid cancer associated with APC mutation in codon 1061; this is true both in absolute numbers of patients reported as well as when adjusted to the frequency of APC mutations at this locus in an unselected population." (PMID 24093640, 2013). "However, Shubadha and Bagwan explained that the potential absence of polyps during colonoscopy and germline mutations in the adenomatous polyposis coli (APC) gene provide evidence that the tumor is a sporadic counterpart of FAP-associated thyroid carcinoma." (PMID 22432054, 2011). "A meta-analysis that investigated thyroid cancer in FAP analyzed 9,821 patients and found that 79.2% of those who developed thyroid cancer had a GPV in the APC mutation cluster region (codons 1286–1513), and 95% of these cases were female." (PMID 41214301, 2026). "The results of this study yield new insights on WDTC, showing that inherited variants in the APC and GNAS genes can play a role in the etiology of thyroid cancer." (PMID 28410400, 2017). "Thirteen of fifteen patients with thyroid carcinoma and FAP had mutations in the APC gene between codons 778 and 1309 in a study by Cetta." (PMID 24093640, 2013). "To date, there are no data indicating an increased incidence of thyroid cancer in LS patients, in contrast with patients carrying mutations in other genes, such as APC or PTEN." (PMID 37894428, 2023). "Moreover, APC mutations are associated with RET/PTC1 gene rearrangements in patients with FAP and thyroid cancer." (PMID 35626065, 2022). "However, overexpression of miR-155 in thyroid cancer cell lines decreased APC expression at a transcript and protein level, increasing proliferation and tumorigenic capacity, suggesting miR-155 as a regulator of this pathway." (PMID 36499743, 2022). "Therefore, they suggested that in patients with FAP and thyroid cancer, the APC/β-catenin signaling pathway may play an important role in the pathogenesis of this cancer." (PMID 35626065, 2022). "Additionally, given the roles of CHEK2 and APC in key cellular pathways, targeted therapies that aim to restore normal function in these pathways could hold promise for the management of secondary thyroid cancer in childhood cancer survivors." (PMID 39860595, 2025). "Moreover, WES data indicate the presence of APC and RASAL1 gene alterations in various thyroid cancer subtypes." (PMID 35626065, 2022). "This indicates a possible TSG role for both APC and RASAL1 in thyroid cancer development." (PMID 35626065, 2022). "The results show that the expression level of APC correlated with the progression of kidney renal cell carcinoma, testicular germ cell tumor, thyroid carcinoma, lung squamous cell (P < 0.05), but not others." (PMID 35303016, 2022).
thyroid cancer (continued). "It is concluded that, at least in patients not affected by FAP, APC gene abnormalities do not seem to play a relevant role in the pathogenesis of thyroid carcinoma." (PMID 7981058, 1994).
osteosarcoma (28 papers, 2003 to 2025). A usually aggressive malignant bone-forming mesenchymal neoplasm, predominantly affecting adolescents and young adults. "The Wnt pathway, including somatic APC mutations, is also known to be implicated in the development of osteosarcomas, for which we found an association with tooth agenesis in adolescence." (PMID 38488796, 2024). "One case of primary osteosarcoma reported an APC gene polymorphism." (PMID 38903727, 2024). "Similarly, amplifications of MYC, BRCA2, and a co‐amplification of the region PDGFRA–KIT occurred mostly in recurring tumors (P1, P2, P4, P6, P7, P10), whereas JUN and APC mutations occurred in a single osteosarcoma primary (P1)." (PMID 33963544, 2021). "For instance, circLRP6 was shown to promote osteosarcoma progression through inhibiting APC and KLF2 expression." (PMID 33103338, 2021). "KIF18B regulated β-catenin expression at the transcriptional level by controlling nuclear aggregation of ATF2 and at the post-transcriptional level by interacting with the adenomatous polyposis coli (APC) tumor suppressor gene in osteosarcoma cells." (PMID 32587775, 2020). "Taken together, these results indicate that the degradation of BRD7 by APC/C E3 ligase plays key roles in osteosarcoma." (PMID 24840027, 2014). "The combination of proTAME, an inhibitor of APC/C, with chemotherapeutic drugs efficiently targets osteosarcoma in vitro." (PMID 24840027, 2014). "Results at the locus 7q31 and at the region containing APC suggested a striking and interesting role for these sites in osteosarcoma oncogenesis, even though the frequencies of rearrangements at the locus 7q31 were rather low (34%)." (PMID 12799638, 2003). "Moreover, BUB1–PLK1 complex mediate the phosphorylation of Cdc20 and inhibit the anaphase-promoting complex or cyclosome (APC/C) which result in the promotion of spindle checkpoint signaling in cervical cancer and osteosarcoma." (PMID 31488217, 2019). "Collectively, our results indicate that targeting the APC/C-BRD7 pathway may be a novel strategy for treating osteosarcoma." (PMID 24840027, 2014). "Our observation that APC suppression reduces tumor cell migration is consistent with functional studies indicating that APC is required for directed cell motility in astrocytes, as well as protrusion formation and wound filling in fibroblasts and osteosarcoma cells." (PMID 23302090, 2013). "Furthermore, the oncogene effect of circLRP6 on osteosarcoma can be reversed with APC." (PMID 33103338, 2021). "The authors highlighted the role of the LOX-1 receptor in various cancers, such as glioblastoma and osteosarcoma, and evidence of its interaction with the WNT/APC/beta-catenin signaling pathway." (PMID 39445018, 2024). "CircRNA LRP6 accelerates the development of osteosarcoma through regulating KLF2 and APC expressions." (PMID 33958507, 2021). "A previous study suggested that highly expressed circLRP6 was related to the worse overall survival in osteosarcoma, and circLRP6 promoted osteosarcoma tumorigenesis by downregulating KLF2 and APC expression level." (PMID 34158077, 2021). "For example, the adenomatous polyposis coli (APC) is a classic tumor suppressor, and it was repressed by HIF‐1α via a functional HRE on the its promoter in osteosarcoma and colon cancer cells." (PMID 33463054, 2021). "Conversely, when the APC/C complex is inhibited by small-molecule inhibitors, such as pro-TAME, the BRD7 protein is stabilized and suppresses osteosarcoma tumor progression." (PMID 24840027, 2014). "It is well established that the CSN interacts physically with the APC/C and regulates several targets including Cyclin A and Cdc6 in human U2OS osteosarcoma cells." (PMID 21991377, 2011). "At the locus 5q21, the use of two microsatellites, surrounding the APC gene, increased the specificity of allelotyping at this site and allowed us to speculate that the high percentage of rearrangement could strengthen the fundamental role of this gene in osteosarcoma." (PMID 12799638, 2003).
osteosarcoma (continued). "For example, CircRNA LRP6 promotes osteosarcoma development by targeting KLF2 and APC." (PMID 34224315, 2021). "In osteosarcoma, miR-135b promotes cell proliferation and invasion by targeting FOXO142 and stimulates recurrence and lung metastasis by targeting TET3 and multiple negative regulators of the Wnt/β-Catenin, including APC, CK1α, GSK3β, and β-TrCP43." (PMID 33990540, 2021). "Inhibiting APC/C activity, which participates in promoting osteosarcoma cell growth and tumor formation, decreases degradation of BRD7 and reduces the proliferation of cells in osteosarcoma." (PMID 32992509, 2020). "In this study, we found that APC/Ccdh1 and APC/Ccdc20 directly bind and degrade BRD7, a finding that is clinically relevant because a strong inverse correlation between the expression levels of BRD7 and Cdh1 or Cdc20 was observed in patients with osteosarcoma." (PMID 24840027, 2014). "Up to now, the status of many differentiation and proliferation genes such as c-met or APC, which are known to be involved in other cancers have not yet been analysed in paediatric osteosarcomas." (PMID 12799638, 2003). "Since osteosarcomas are histologically characterized by malignant osteoblasts producing an osteoid component, this research team examined the genomic status of MET, TWIST, and APC genes involved in ossification processes in pediatric osteosarcomas treated with the OS94 protocol." (PMID 38596618, 2024). "In this report, we demonstrate that BRD7, as a new substrate of APC/C-E3 ligase during the cell cycle, is a tumor suppressor in osteosarcoma, and this APC/C-BRD7 pathway may provide a potential therapeutic target for treating osteosarcoma." (PMID 24840027, 2014). "Given that the APC/C-BRD7 pathway plays key roles in cell growth and the tumorigenesis of osteosarcoma, which has a poor prognosis because of chemoresistance, we investigated whether apoptosis induced by chemotherapeutic drugs could be enhanced by inhibiting the APC/C-BRD7 pathway in osteosarcoma." (PMID 24840027, 2014).